PHF6 (PHD finger protein 6)
Description:
Transcriptional regulator that associates with ribosomal RNA promoters and suppresses ribosomal RNA (rRNA) transcription.
Synonyms: CENP-31; KIAA1823; MGC14797; BFLS; BORJ
Tractability: PROTAC: UniProt records ubiquitination sites on it; ubiquitination databases record sites on it; its protein half-life has been measured.
Gene: Protein-coding gene on chromosome X (134,373,286 to 134,428,792, forward strand). Ensembl gene ENSG00000156531.
Subcellular location: Nucleus; Nucleus, nucleolus; Chromosome, centromere, kinetochore
Subcellular location (Human Protein Atlas): Nucleoli; Nucleoplasm
Pathways (Reactome):
Chromatin organization: Interaction of NuRD complexes with transcription factors
Gene Ontology:
Molecular function: enzyme binding; histone binding; histone deacetylase binding; phosphoprotein binding; protein binding; ribonucleoprotein complex binding; RNA binding; scaffold protein binding; tubulin binding
Biological process: negative regulation of transcription by RNA polymerase II; regulation of transcription by RNA polymerase II
Cellular component: nucleolus; nucleoplasm; nucleus
Gene-disease validity (ClinGen):
ClinGen rates the evidence that PHF6 causes each of these diseases.
Borjeson-Forssman-Lehmann syndrome (X-linked): Definitive. A X-linked yndrome characterized by intellectual deficit, truncal obesity, characteristic facial features, hypogonadism, tapered fingers and short toes.
Cancer hallmarks: proliferative signalling (promotes); change of cellular energetics (promotes); escaping programmed cell death (promotes); genome instability and mutations (suppresses); suppression of growth (promotes); invasion and metastasis (promotes)
Homologues: Orthologues: chimpanzee PHF6 (100% identical), macaque PHF6 (100% identical), dog PHF6 (99% identical), pig PHF6 (99% identical), rabbit PHF6 (99% identical), guinea pig PHF6 (99% identical), mouse Phf6 (97% identical), rat Phf6 (97% identical), tropical clawed frog phf6 (77% identical), zebrafish phf6 (71% identical), Drosophila melanogaster Phf7 (11% identical), Drosophila melanogaster pie (11% identical). Paralogues in human: PHF11 (21% identical), G2E3 (15% identical), PHF7 (11% identical).
Diseases named in the same sentence as PHF6 in open-access papers:
PHF6 is named in the same sentence as 88 diseases in open-access papers, as found by Europe PMC text mining. Sharing a sentence is not in itself a finding about the gene and the disease. The quoted sentences say what the papers report.
leukemia (31 papers, 2012 to 2025). A malignant (clonal) hematologic disorder, involving hematopoietic stem cells and characterized by the presence of primitive or atypical myeloid or lymphoid cells in the bone marrow and the blood. "Our work indicates that Phf6 loss increases AML self-renewal through context-specific effects on leukemia stem cells." (PMID 39004675, 2024). "On one hand, mutations in PHD finger proteins like PHF6 exacerbate leukemia progression, while on the other hand, proteins such as UHRF1 regulate essential pathways in ESCC, affecting tumor growth and therapy resistance." (PMID 38813086, 2024). "We also found no blood count abnormalities in cKO mice up to 9 months, further indicating that Phf6 loss alone is likely insufficient to initiate leukemia." (PMID 39004675, 2024). "We next sought to determine the effect of Phf6 loss on the frequency of leukemia initiating cells (LIC), the sub-population of transformed marrow capable of initiating leukemia." (PMID 39004675, 2024). "This binding is highly conserved in the nucleoplasm, and thus mutations in PHF6 have been studied extensively in the field of cancer, especially leukemia; however, the effects of RBBP4 in mutated PHF6 are still less studied." (PMID 38028543, 2023). "It has been reported that alterations in PHF6, a highly conserved epigenetic transcriptional regulator, are key epigenetic mechanisms associated with leukaemia initiation and progression." (PMID 36756714, 2023). "Among the PHD finger-containing protein (PHF) families, PHF6 is well-known to be a key factor in leukemia with several disease-driving mutations." (PMID 36967443, 2023). "We found that PHF6 mutations frequently coexist with JAK3 mutations in T-ALL patients, and Phf6 comutation with JAK3 can drive aggressive leukemia in mice." (PMID 34465864, 2022). "To identify the definitive role of Phf6 deficiency in leukemia cell over-proliferation, we investigated cell cycle and apoptosis in VC Phf6 + JAK3M511I cells." (PMID 34465864, 2022). "Here we examined the role of cooperatively PHF6 mutations in the context of JAK/STAT mutant-induced leukemia in patients and further functionally dissect their biological events using JAK3M511I T-ALL mouse model." (PMID 34465864, 2022). "To evaluate the potential role of PHF6 mutation in leukemia-initiating events, we generated Phf6 knockout (Vav1-Cre;Phf6fl/y) and wild-type (Phf6fl/y) mice." (PMID 34465864, 2022). "Myeloid neoplasms with SF3B1 and PHF6 double mutations tend to show morphologic evidence of myelodysplasia, increased reticulin fibrosis, an increased blast count, and the risk of leukemia transformation." (PMID 36671709, 2022). "The association of PHF6 mutations with leukemias of ambiguous lineage further supports a role for these mutations in lineage plasticity." (PMID 34381727, 2021). "This was confirmed by the observation of accelerated leukemia development upon introducing PHF6 mutations in NOTCH1-driven murine T-ALL models, partly by elevating the leukemia stem cell numbers." (PMID 33251223, 2020). "For example, PHF6 is mutated in the human disease Börjeson–Forssman–Lehman syndrome and in human leukemia." (PMID 25866244, 2015). "PHF6 mutations co-occur in MDS/AML with mutations in RUNX1, ASXL1, and U2AF1, with the majority of PHF6 mutations being frameshift and nonsense mutations distributed throughout the gene body, predicted to produce null alleles and indicating that PHF6 acts as a leukemia suppressor." (PMID 39004675, 2024). "To determine whether Phf6 deficiency suppresses AML progression by decreasing LSCs (leukemia stem cells) number and activity, we analyzed the frequency and absolute number of c-Kit+ and L-GMP (Lin− c-Kit+ IL-7R− Sca-1− CD16/32+ CD34+) LSCs in BM and spleen." (PMID 38336746, 2024). "The combined clinical data suggested that PHF6 mutations may play a synergetic role with JAK/STAT mutations in leukemia development." (PMID 34465864, 2022).
leukemia (continued). "It indicated that the role(s) of PHF6 may depend on the combination of oncogenic mutations and specific molecular pathways that drive leukemia." (PMID 34465864, 2022). "Notably, the expression of TCR-β was significantly decreased in Phf6-deficient leukemia cells, suggesting that VC Phf6 + JAK3M511I cells were more immature." (PMID 34465864, 2022). "Nevertheless, Phf6 loss could significantly accelerate leukemia development driven by aberrant expression of TLX3 or lower the threshold of NOTCH1-induced T-ALL development." (PMID 34465864, 2022). "We analyzed cell immunophenotype and morphology and found that the differentiation of AML cells with PHF6 deletion tended to the more mature stage, which meant that such leukemia cells had low malignancy." (PMID 38336746, 2024). "We found that leukemia cells in the two Phf6 KO groups showed a tendency towards maturity with smaller and lobulated nuclei compared to the controls with larger cell size and round nuclear contours." (PMID 38336746, 2024). "By investigating the clinical database of leukemia patients (data from bloodspot, oncomine and gepia datasets), we found that PHF6 was highly expressed in AML cells and was consistent with MLL rearrangement." (PMID 38336746, 2024). "The infiltration of leukemia cell in the liver and lung were decreased in the two Phf6 KO groups than the control mice." (PMID 38336746, 2024). "What interests us is that PHF6 knockout at a later disease stage seems to have a better leukemia inhibition effect." (PMID 38336746, 2024). "This interaction suggests PHF6’s essential function in leukemia development and underscores the potential of combining JAK3 and MDM2 inhibitors as a targeted therapy for T-ALL patients with co-mutation of PHF6 and JAK3." (PMID 38813086, 2024). "The results from the serial transplantation suggested that the Phf6 KO mice showed less aggressive leukemia phenotypes." (PMID 38336746, 2024). "This disruption reduces the proliferation of myeloid leukemia cells and impacts the self-renewal ability of leukemia stem cells (LSCs), suggesting a pro-oncogenic role for PHF6 in myeloid leukemia." (PMID 38813086, 2024). "The percentage of GFP+ leukemia cells decreased in Phf6 KO groups than in PBS control groups in the BM and spleen." (PMID 38336746, 2024). "We examine the role of hematopoietic Phf6 deletion on AML progression and show that Phf6 loss accelerates AML progression over serial transplantation, accompanied by an accumulation of leukemia initiating cells (LICs)." (PMID 39004675, 2024). "The infiltration degree of leukemia cells in the bone, spleen, and liver were reduced in the two Phf6 KO groups compared to the control mice." (PMID 38336746, 2024). "Further, we examined PHF6 protein in BM leukemia cells at Day 21 post pIpC to confirm the deletion of PHF6 through the method of western blot." (PMID 38336746, 2024). "We also found that the proliferation of c-Kit+ leukemia cells with PHF6 deletion was significantly inhibited." (PMID 38336746, 2024). "The percentage of GFP+ leukemia cells and the degree of extramedullary infiltration in the liver, spleen, brain and lung also decreased in VC Phf6,RE9a mice than that of WT Phf6,RE9a mice." (PMID 37393343, 2023). "Depletion of Phf6 significantly decreased the growth of leukemia cells in Em-Myc B-ALL mouse model and prolonged the survival of BCR-ABL induced B-ALL mouse model in vivo." (PMID 37393343, 2023). "Another CN-LOH region of interest was identified in sample S5, showing CN-LOH of Xq25–qter, involving four genes (STAG2, BCORL1, PHF6, and BRCC3) that have previously been implicated in different types of leukemias." (PMID 36831635, 2023). "In the current study, we found that PHF6 is essential for the maintenance of self-renewal ability of leukemia stem cells (LSCs) but dispensable for hematopoietic stem cells (HSCs) in vivo." (PMID 37393343, 2023).
leukemia (continued). "The survival of leukemia cells was sensitive to PHF6 depletion in both RUNX1-ETO9a (RE9a) and MLL-AF9 (MA9) AML mouse models and in human AML cell lines." (PMID 37393343, 2023). "Some pluripotency genes were also identified, as well as cancer genes, such as TET1, ALK, EP300, ERG, MKL1 and PHF6, already described as being involved in leukemia." (PMID 37174060, 2023). "We further demonstrated that combination therapy with tofacitinib and idasanutlin reduced the Phf6 KO + JAK3M511I leukemia burden in vivo." (PMID 34465864, 2022). "The percentage of GFP+ leukemia cells was higher in the peripheral blood (PB) of VC Phf6 + JAK3M511I mice than Phf6 WT + JAK3M511I mice." (PMID 34465864, 2022). "The VC Phf6 + JAK3M511I mice showed more aggressive leukemia phenotypes than Phf6 WT + JAK3M511I mice, including higher white blood cells (WBCs), neutrophils (Neu), and lymphocytes (Lym) in PB." (PMID 34465864, 2022). "We found that the average survival time is shorter in patients with JAK/STAT and PHF6 comutation than that in other patients, suggesting a potential role of PHF6 in leukemia progression." (PMID 34465864, 2022). "While all mice succumbed to leukemia, the survival time of VC Phf6 + JAK3M511I mice was significantly shorter than Phf6 WT + JAK3M511I mice." (PMID 34465864, 2022). "However, the role(s) of PHF6 mutations in JAK3-driven leukemia remain unclear." (PMID 34465864, 2022). "Our result thus demonstrated that combination therapy with tofacitinib and idasanutlin can reduce leukemia burden better than single drug treatment in Phf6 KO + JAK3M511I mice, which was also validated by the result in human MOLT-4 cells." (PMID 34465864, 2022). "To further identify the properties of VC Phf6 + JAK3M511I leukemia cells, we analyzed T-cell surface markers of GFP+ cells (CD4, CD8, CD25, and CD127)." (PMID 34465864, 2022). "Here, the cooperation between JAK3 activation and PHF6 inactivation is examined in leukemia patients and in mice models." (PMID 34465864, 2022). "Intriguingly, use of a retrovirally-expressed shRNA screening library into a B-lymphobastic leukemia cell line revealed that knockdown of PHF6 levels inhibited cell growth and leukemia growth in transplanted models." (PMID 34381727, 2021). "PHF6 mutations are most common in T-ALL, and appear early in the disease course yet appear insufficient for leukemia development." (PMID 34381727, 2021). "Thus, PHF6 deletion may be associated with leukemia development." (PMID 32766158, 2020). "Recently, the role for PHF6 was described in hematopoietic stem cell homeostasis and T-ALL leukemia initiating cell self-renewal, characterizing PHF6 mutations as early events and drivers of leukemia stem cell activity in the pathogenesis of T-ALL." (PMID 31338319, 2019). "The generation of transgenic mouse models with BFLS-like, T-ALL-like, or AML-like PHF6 mutations, will certainly augment the dissection of the molecular mechanisms driving BFLS and leukemia." (PMID 26103525, 2015). "Comprehensive profiling of TSPAN32 expression across genetically annotated patient cohorts will be necessary to delineate the precise relationship between leukemia subtype, underlying mutations (e.g., NOTCH1, FBXW7, PHF6, HOXA cluster abnormalities), and TSPAN32 regulation." (PMID 41007654, 2025). "Interestingly, the deletion of PHF6 at a later stage of the disease displayed a better anti-leukemia effect." (PMID 38336746, 2024). "Notably, consistent with our findings in stem cell regulation, other groups have also reported a role for PHF6 in cell differentiation and lineage specification in leukemia myeloid cell models." (PMID 38429579, 2024). "PHF6 plays an important role in the occurrence and development of leukemia." (PMID 38336746, 2024).
leukemia (continued). "We speculate that PHF6 deletion at the later stage may have a more common and effective impact on more leukemia cells." (PMID 38336746, 2024). "In T-ALL, over 40% of patients with JAK3 GOF mutations also possessed PHF6 LOF mutations, with this cohort showing reduced survival, while PHF6 inactivation in mice accelerated cell transformation mediated by JAK3 M511I, inducing an aggressive form of leukemia." (PMID 38474223, 2024). "Moreover, loss of Phf6 in leukaemia lymphoblasts activates a leukaemia stem cell transcriptional program and drives enhanced T‐ALL leukaemia‐initiating cell activity." (PMID 36176187, 2023). "Next, we assessed the anti-leukemia efficacy of the NF-κB inhibitor on PHF6 OE AML cells in vivo." (PMID 37393343, 2023). "The proliferative advantage conferred by PHF6 and NF-κB might contribute to the clonal evolution of pre-leukemia cells that lead to leukemia transformation." (PMID 37393343, 2023). "Although PHF6 mutations often occurred in leukemia patients, PHF6 deficiency alone was not sufficient to induce leukemic transformation." (PMID 37393343, 2023). "Furthermore, we found that Phf6 KO promoted GFP+ leukemia cell apoptosis and blocked the cell cycle in the phase of G0." (PMID 37393343, 2023). "PHF6 is reproted to interact with histones to exert functions in leukemia, suggesting that PHF6 could play as a reader of histone modification." (PMID 36967443, 2023). "The percentage of GFP+ leukemia cells in PB was equal in WT Phf6,MA9 and VC Phf6,MA9 AML mice." (PMID 37393343, 2023). "It has been demonstrated experimentally that PHF6 loss can enhance the oncogenic activity of NOTCH1 mutations; therefore, PHF6 and NOTCH1 co-mutation are more tightly linked to T-ALL pathogenesis and leukemia-associated mortality." (PMID 35280829, 2022). "Phf6 deficiency could also activate leukemia stem cell transcriptional programs and enhance T-ALL leukemia-initiating cell (LIC) activity." (PMID 34465864, 2022). "Importantly, secondary leukemia cells arising from VC Phf6 + JAK3M511I primary cells in the BM were mainly lymphoid cells (96.3%), in contrast to the primary VC Phf6 + JAK3M511I cells showed much greater heterogeneity." (PMID 34465864, 2022). "Finally, a network of miRNAs, including miR-19b, miR-20a/93, miR-26a, miR-92, and miR-223, have been shown to target multiple PHF6 and other T-ALL-associated tumor suppressors, and thus promote leukemia." (PMID 34381727, 2021). "In the context of leukemia, PHF6 has been suggested to act as an oncogene in B-ALL." (PMID 33251223, 2020). "In addition, cells from leukemia 241 carried deletions in Runx1 and Phf6." (PMID 40394211, 2025). "Collectively, our data resolves a controversy in the literature by demonstrating that PHF6 suppresses AML stem cell self-renewal in a clinically relevant AML model system, and demonstrates how the loss of a specific repressor of HSC self-renewal drives leukemia stemness." (PMID 39004675, 2024). "Additionally, the percentage of GFP+ c-Kit+ cells was significantly decreased, while the percentage of Mac-1+ cells was increased in the BM of VC Phf6,RE9a mice when compared with that of WT Phf6,RE9a mice, indicating that Phf6 KO promoted the differentiation of RE9a-induced leukemia cells." (PMID 37393343, 2023). "Indeed, ectopic expression of TLX3 in PHF6-deleted mice facilitated early onset leukemia and a hTLX1;PHF6+/- zebrafish model demonstrated fully penetrant early-onset leukemia development, underscoring the role of cooperation between these mutations in leukemogenesis." (PMID 34381727, 2021).